TLR7 (toll like receptor 7)
Diseases named in the same sentence as TLR7 in open-access papers (continued):
Sharing a sentence is not in itself a finding about the gene and the disease.
infection (continued). "Some enteroviruses, such as CVB3, can induce expression of TLR7 during infection." (PMID 31117206, 2019). "Notably, IL-6 mRNA was induced in the cerebral cortex of infected WT mice on 3 and 5 day post-infection, whereas it only slightly induced in the cortex of infected TLR7-/- mice." (PMID 31730654, 2019). "Additionally, our results revealed that VSV drains to pLN in a short period of time after s.c. infection as infectious virus was detected in pLN of both Wt and TLR7−/− mice within minutes after infection." (PMID 30930901, 2019). "In conclusion, we have identified a previously unknown function of TLR7 in ssRNA virus replication within productively infected SCS macrophages using a lymph-borne VSV infection model." (PMID 30930901, 2019). "Similarly, VSV-luciferase infection assessed by in vivo imaging was restricted to the foot skin in TLR7−/− mice." (PMID 30930901, 2019). "Next, we compared the kinetics of infection in the pLN of Wt and TLR7−/− mice." (PMID 30930901, 2019). "Transfer of TLR7-competent, but not TLR7-deficient pDCs led to a significantly diminished virus recovery in TLR7−/− animals on day 7 after infection with PVM indicating that TLR7-mediated signaling by pDC is required for appropriate innate responses to acute PVM infection." (PMID 31031767, 2019). "By contrast, a significant production of Il-12p40 was detectable in WT mice by day 4 post infection, whereas only a marginal and not significant increase in Il-12p40 was detected in TLR7-deficient mice." (PMID 29497422, 2018). "This did not relate to decreased phagocytosis with Tlr7-deficiency given that bacterial survival was significantly greater in Tlr7-deficient BMMs after 1 h infection." (PMID 29616197, 2018). "However, in placenta cells, we saw that siRNA against TLR8 significantly decreased AXL expression after three days, with a similar downregulation also observed after TLR7 knockdown three days after infection." (PMID 30453684, 2018). "Nonetheless, further in vivo infection studies in another colony of C57BL/6 or BALB/c Tlr7-deficient mice will be necessary to firmly rule out a role of Tlr7 on S. Typhimurium infection." (PMID 29616197, 2018). "TLR7−/− mice infected with rJHMVWT succumbed to infection, while we observed no increase in weight loss or lethality after infection with rJHMVPS−." (PMID 29717007, 2018). "Here we show that infection of plasmacytoid dendritic cells (pDCs) with a recombinant virus lacking SH expression (rhMPV-ΔSH) enhanced the secretion of type I interferons (IFNs), which required TLR7 and MyD88 expression." (PMID 29789500, 2018). "At 24 h after infection, the following genes were upregulated in infected macrophages transfected with the let-7e inhibitor compared to macrophages transfected with NC: Tlr7, Ly96/MD-2, Casp8, Map3k1, Mapk8, Ptgs2/Cox2, Csf 3/GCSF, and the ubiquitin-conjugating enzyme E2N (Ube2n)." (PMID 30555476, 2018). "In RSV, TLR7 appears to have an important role in promoting a non-pathogenic T cell response to infection." (PMID 29552008, 2018). "At 48 h post-infection, there was a significant rise in TLR7 expression (p < 0.001)." (PMID 28265274, 2017). "Thus, while in WT mice both FO and T1 B cells upregulated TLR7 upon infection, in BAFFR-/- mice T1 B cells were the major B cell subset responding to WNV that increased TLR7 expression." (PMID 29176765, 2017). "IOE infection of TLR7-/- BMM elicited IL-1β at slightly lower levels when compared to WT-BMM." (PMID 29049365, 2017). "Allogeneic T cell stimulation by spleen cells of LDV‐infected wild type, but not TLR‐7‐deficient, mice was severely compromised after infection which coincided with selective elimination of CD11b+ and CD8α+ cDCs from the spleen." (PMID 28474504, 2017). "TLR7/9-/- mice showed significantly increased fungal burden in the lungs by 10 dpi, which corresponds to when the majority of these mice begin to succumb to infection." (PMID 27459510, 2016).
infection (continued). "There was a moderate up-regulation for TLR-3 and TLR-7 in CK/SD/w3 and CK/SD/w4 infection." (PMID 27446066, 2016). "Pigeon TLR7 gene expression in spleen of pigeons injected with R848 was slightly but significantly increased (1.4-fold) over the control pigeons 1 and 3 days post-infection (d.p.i.)." (PMID 25874762, 2015). "After Newcastle disease virus vaccine strain LaSota inoculation and agonist R848 injection, the level of TLR7 mRNA in the spleen of pigeons increased significantly in the R848-injected group, but decreased in the LaSota-inoculated group at three day post-infection (d.p.i.)." (PMID 25874762, 2015). "However, the expression of TLR3 and TLR7 was downregulated in response to SS-10 infection at 72 hpi (0.61 and 0.41-fold, respectively)." (PMID 26635752, 2015). "Concomitantly, the immunoregulatory effect of TLR2 stimulation by GPI-mucin in dendritic cells may also balance TLR9 and TLR7 activation by parasite DNA and RNA, respectively, at least in the initial phases of infection." (PMID 26834737, 2015). "In the present study, we hypothesized that MSCs may modulate TLR7/8-mediated signaling, a major signaling pathway activated by infection with ssRNA viruses such as influenza virus and HIV." (PMID 24191131, 2013). "In order to determine whether this effect was specific for IAV, MDDCs were treated with agonists for the Toll-like receptors (TLR) 3, TLR4 and TLR7/8 (Poly I:C, LPS, R848 respectively) for either 4 h or 24 h prior to infection with SP." (PMID 23421931, 2013). "The levels of TLR3-4 and TLR7-9 were increased 3 h after hMPV infection." (PMID 24039959, 2013). "Moreover, in the same model, Cox1 deletion is associated with worsening of infection, consistent with our data demonstrating that COX-1 can limit TLR7/9 interferon responses." (PMID 23850620, 2013). "The role of TLR7-8 pathway in the anti-viral immune response in mice, may be different from which in human infection." (PMID 24039959, 2013). "In addition to synthetic ligands we also showed that exposure of KSHV latently infected B cells to secondary infection with the known TLR7 agonist, VSV, led to significant reactivation of KSHV." (PMID 23061052, 2012). "The linkage between TLR7 and LMP1 expression is intriguing: primary infection of B lymphocytes by EBV may induce the expression of TLR7, IRF5, and IRF7." (PMID 22952664, 2012). "It is likely that Heat-VAC infection of pDCs produces long, uncapped and partially double-stranded viral RNA transcripts that are sensed by the endosomal RNA sensor TLR7, which utilizes its adaptor MyD88 to activate transcription factor IRF7, resulting in the induction of type I IFN." (PMID 22606294, 2012). "Lymph node mDC remained responsive to stimulation with a TLR7/8 agonist during infection." (PMID 21203477, 2010). "In contrast, in our study pDC from blood and lymph nodes in monkeys 14 days after SIVmac251 infection were largely normal in their response to TLR7 stimulation, with lymph node pDC producing TNF-α and IFN-α together at high levels that were indistinguishable from controls." (PMID 19424421, 2009). "Moreover we recently identified an important role for CYLD in modulating host antiviral response by regulating TLR7 expression in mixed infection of bacteria and virus." (PMID 18664270, 2008). "In contrast, patients unable to induce TLR7 in early infection stages may develop a severe disease." (PMID 41445728, 2025). "Similarly, mucosal-MNV infection upregulated intact TLR7 expression in Ncf190H mice." (PMID 39939342, 2025). "Additionally, we identified a significant increase in the TLR2 and TLR7 mRNA levels, along with activation of NF-kB-complex during the eclipse period of infection, suggesting an essential role of those TLRs in sensing DENV-ssRNA and/or structural PAMPs in viral particles by macrophages." (PMID 40934228, 2025).
infection (continued). "Similarly, the chemokines CCL2 (attracting monocytes), CXCL2 (attracting neutrophils), CCL5 (attracting T cells), CXCL10 (attracting activated T cells, eosinophils), and CCL11 (eosinophils) were elevated during infection with a significant reduction in TLR7 KO mice." (PMID 39769461, 2024). "However, our data suggest that chronic TLR7 suppression during acute infection might lead to a shift towards a heightened Th2 response and suppressed Treg response, potentially increasing airway hyperreactivity and allergen sensitivity." (PMID 39769461, 2024). "Using in vitro infection, monocytes from seropositive cats had decreased levels of TLR7 expression, and uninfected monocytes had increased levels of TLR7, leading the authors to hypothesize that TLR7 might be a key factor in the viral evasion of the innate immune response." (PMID 38257841, 2024). "At the laboratory, controlled experimental infections, using genetically well‐characterized individuals would bring the evidence that TLR‐7 is indeed involved in the adaptation to H. pinnae and could also allow to assess the level of associated stress response." (PMID 37546570, 2023). "After the infection, the percentage of splenic ProE or splenic EryA in wild-type mice was higher than in TLR7-/- mice, however, the percentage of splenic EryB in wild-type mice and TLR7-/- mice were similar, resulting in a lower percentage of splenic EryC in wild-type mice than in TLR7-/- mice." (PMID 37180169, 2023). "A greater type I IFN response, as observed in our RSV-infected TLR7 KO mice at 4 dpi, improves the rate of viral clearance and reduces pathology, thus infection with RSV A Long may represent a less severe, acute model in comparison to some other viral subtypes." (PMID 37795093, 2023). "For instance, endosomal TLR3 and TLR7, and cytosolic retinoic acid-inducible gene I (RIG-I) and melanoma differentiation-associated protein 5 (MDA5) have been shown to sense the DENV RNA early in the infection, thereby leading to the production of type I interferons." (PMID 36240261, 2022). "In other words, the inhibition of the RLR pathway, a sensor of viral RNA in the cytoplasm, might offer a clue as to why the initial innate immune response is very dependent on functional TLR7-signaling, an endosomal sensor for viral RNA, in the case of infection with SARS-CoV-2." (PMID 35065665, 2022). "However, the magnitude of impact on TLR7 signaling is less striking during infection." (PMID 33673546, 2021). "However, TLR7 KO mice had a shorter survival time after infection than WT mice." (PMID 34692568, 2021). "Collectively, these findings indicate that the latency reversing effect of TLR7 agonists in NHPs might be very sensitive to alterations in model conditions such as timing of treatment initiation in relation to the course of infection, immune status, and SIV/SHIV challenge strain." (PMID 32595636, 2020). "It was also interesting to note that female mice infected with TMEV eventually showed low but detectable levels of autoantibodies, suggesting that TMEV infection might also trigger autoimmune responses at a much slower rate under conditions of normal TLR7 expression." (PMID 32727036, 2020). "It is also possible that TLR7-mediated signaling creates a pool of actively dividing cells that are highly susceptible to MLV at early times post-infection, but in the long term, TLR7 signaling is needed to generate the innate immune response leading to adaptive immunity and infection control." (PMID 32751803, 2020). "Interestingly, these results are similar with previous findings that levels of TLR-7 and TLR-3 mRNA are barely up-regulated in response to highly pathogenic H7 infections, while rapid upregulation occurs following a lower pathogenic H7 infection." (PMID 30823888, 2019).
infection (continued). "This study revealed that LEP and DPEP could down-regulate the activity of NF-κB p65 by regulating MyD88-dependent signaling pathways of TLR4 and TLR7, thereby exerting their antiviral effects, and the treatment effects might be more significant in the early phase of infection." (PMID 31551774, 2019). "Furthermore, in comparison to oseltamivir, 20 mg/kg LEP or DPEP could dramatically inhibit the protein expression of TLR4, TLR7 and NF-κB p65 on day 3 post-infection (P < 0.01 or P < 0.05)." (PMID 31551774, 2019). "Furthermore, we tested whether the difference in LN infection between Wt and TLR7−/− mice was restricted to the early phase until 12 h p.i. by performing a kinetic analysis in dLN at later time points." (PMID 30930901, 2019). "Similar to the primary PVM infection, the inflammatory response in the BAL (defined by the number eosinophils, neutrophils, mononuclear cells and lymphocytes) of re-infected RAGE deficient mice was comparable to WT mice and markedly lower than that of re-infected TLR7 deficient mice." (PMID 28099113, 2017). "Therefore, the importance of TLR7 for the induction of IFN-β expression may be more critical during infection by Y. pestis strains that survive in the intracellular compartment than during infection by bacteria that are killed there." (PMID 28847850, 2017). "Thus, TLR7/8 triggering may have a dichotomous effect in HIV infection by preventing infection of CD4+ T cells while activating HIV expression in others." (PMID 27799218, 2017). "A more recent study showed that the three nucleic acid sensing TLRs, TLR3, 7 and 9, are crucial for a protective response against L. major infection, as mice which lacked all of these functional TLRs (i.e. TLR3/TLR7/TLR9−/− or UNC93B1−/− mice) were highly susceptible to infection." (PMID 27716391, 2016). "Similarly, in buffalo, the TLR-7 mediated type I IFN response upon infection may afford resistance to PPRV." (PMID 25369126, 2014). "We hypothesize that the lack or inconsistent impact of TLR7/MyD88 on acute FV infection may reflect the fact that the neutralizing antibody responses do not play a significant role in inhibiting FV at the earliest infection time points." (PMID 25539593, 2014). "TLR7 expressed within plasmacytoid dendritic cells (pDCs) may also sense infection in other cells." (PMID 23717201, 2013). "As expected, the anti-miR-155 antagomir abrogated the poly(I∶C)-induced miR-155 increase, and this resulted in a significantly higher susceptibility to infection, which became more similar to that observed in TLR7-stimulated MDMs that do not display increased miR-155 levels." (PMID 23028330, 2012). "Interestingly, we could not detect any upregulation of IRF-5 mRNA expression in splenic T-cells from infected Tlr7-/- mice at d28 p.i., suggesting that TLR7 is essential for the induction of IRF-5 in T-cells in the spleen at later stages of infection." (PMID 21253574, 2011). "On the other end, the absence of a significant TLR3 upregulation and low TLR7 and 9 up-regulation compared to the susceptible mice the infection could hint at a possible mechanism by which LPS could enhance their response to the TMEV." (PMID 19094215, 2008). "However, dual inhibition of TLR7 and TLR8 may pose an increased risk of infections." (PMID 40910948, 2026). "We observed that M-CSF-differentiated BMDMs minimally expressed CD103 at baseline but showed robust upregulation after exposure to endosomal TLR ligands (TLR3, TLR7, TLR9) or infection with LCMV." (PMID 40630637, 2025). "We detected fairly high amounts of both TLR7 and TLR8 transcripts, which remained unchanged upon infection." (PMID 39963132, 2025). "Our results revealed a significant parabolic increase in TLR2, TLR4, TLR7, and TLR10 expression following infection, with TLR2—the primary receptor for S. aureus recognition—showing the most pronounced response." (PMID 41305370, 2025).
infection (continued). "While DENV-2 infection-induced up-regulation of TLR2 and TLR7 mRNA during the early stages of infection (1.5 and 3 h.p.i), the mRNA expression of TLR2, TLR3, TLR4, TLR7, and TLR8 reaches its maximum peak of expression at 24 h.p.i." (PMID 40934228, 2025). "In the Lim study, cART was initiated during the chronic phase of infection, 65 days after SIV infection, with TLR7 agonist treatments beginning approximately 440 days after cART initiation." (PMID 41055409, 2025). "In mature chicken BmDCs, 6 h of infection with NDV LaSota was shown to increase the expression of MDA5, LGP2, TLR3, TLR7, and type I IFN IFN-α and IFN-β." (PMID 39967657, 2025). "SARS-CoV-2 sensing is not mediated via engagement of surface TLRs, but rather depends on infection via an ACE2-independent mechanism involving the alternative receptor CD147 and triggering endosomal ssRNA-sensing TLR7/8." (PMID 39963132, 2025). "Individuals with certain TLR7 and TLR8 gene SNPs (e.g., rs3853839, rs3764879, rs179010, rs5741880) showed a higher risk of CHIKV infection, suggesting that while TLR7/8 pathways provide an antiviral role, specific gene variants may compromise their protective role and facilitate infection." (PMID 40872941, 2025). "Our results show that calf tracheal tissues revealed significantly elevated expression levels of TLR2, TLR4, TLR7, and TLR10, as well as MyD88 after infection with M. bovis, and initiated the innate immunity Toll-like receptor signaling pathway." (PMID 40005807, 2025). "In leukocytes, expression of F13A1 (forming coagulation FXIII) correlated with TLR7, TLR9, RIG-I, MDA5, and LGP2, and with infection the correlations changed to TLR6 and CGAS." (PMID 40825056, 2025). "The effect of toll-like receptor 7 (TLR7), which detects viral RNA to initiate antiviral and proinflammatory responses to IAV, on lung function during peak infection and in the resolution phase is not fully understood." (PMID 39769461, 2024). "After 7 days of infection, the levels of Th1 cytokines IFNγ, IL-6, and TNFα were elevated in the BALF, but these levels were significantly reduced in TLR7 KO mice." (PMID 39769461, 2024). "As VFRA is more resistant to these killing processes, it would release less DNA and ssRNA in the lysosome, explaining the increase in TLR7 and TLR9 activation only with the Y strain infection." (PMID 39000601, 2024). "It is known that infection with the SARS-CoV-2 virus is accompanied by an increase in the expression of TLR3 and TLR7." (PMID 39457048, 2024). "Herein, we found that TLR7 was involved in the infection process of RABV, and that the TLR7/Myd88/NF-κB signaling pathway was activated." (PMID 39273091, 2024). "Leukocytes expressing TLR2, TLR3, TLR4, TLR6, and TLR7 also interact with RSV, promoting immune responses post-infection." (PMID 38892370, 2024). "Analysis of T cell populations in the lungs revealed similar increases in T regulatory cells (Treg) and CD8+ cytotoxic T cells following infection in both genotypes at 7 dpi, while significantly more CD4+ helper T cells were found in TLR7 KO mice." (PMID 39769461, 2024). "These cells recognize viral RNA through recognition receptors such as TLR3, TLR7, and TLR8 and respond to infection by secreting inflammatory cytokines." (PMID 38268832, 2024). "Both WT and TLR7 KO mice displayed similar increases in CD8+ cytotoxic T cells in response to infection; however, the proportion of these cells expressing CD69 was significantly lower in TLR7 KO mice." (PMID 39769461, 2024). "Six TLRs recognize the presence of SARS-CoV-2 (TLR2, TLR3, TLR4, TLR7, TLR8, and TLR9), of which TLR2, TLR4, and TLR9 favor the pathogenicity of the virus, while TLR3, TLR7, and TLR8 favor control of the infection and resolution of the disease." (PMID 39062904, 2024). "Upon infection, influenza viruses trigger innate immune responses mediated by PRRs, such as TLR3, TLR7, TLR8, cytosolic receptor RIG-I, and NOD-like receptor NLRP3." (PMID 38892370, 2024).